EGF (epidermal growth factor)
Diseases named in the same sentence as EGF in open-access papers (continued):
Sharing a sentence is not in itself a finding about the gene and the disease.
breast carcinoma (continued). "Therefore, to assess if lipid raft disruption and EGF treatment affect peroxiporin activity, we evaluated H2O2 membrane permeability by measuring the rate of ROS accumulation due to H2O2 influx in breast cancer cells." (PMID 37175840, 2023). "It has also been revealed that EGF/EGFR could phosphorylate ER (ser118 and 167) and initiate downstream MAPK signaling in breast cancer cells, as well as STAT5b and PRLR transcription." (PMID 37415164, 2023). "In this study, we analyze how FGF1, compared to EGF, affects the survival of the MCF-7 model cell line, extensively applied in breast cancer research and treated with taltobulin, a cytotoxin belonging to the widely used group of drugs that inhibit tubulin polymerization." (PMID 37509496, 2023). "Accordingly, breast cancers are classified as tumors expressing estrogen receptor-α (ERα/ESR1), progesterone receptor (PGR) and/or epidermal growth factor (EGF) family receptor HER2/ERBB2, which emanate from luminal epithelial progenitors and are classified as luminal-A or -B." (PMID 36171192, 2022). "Likewise, growth factors such as epidermal growth factor (EGF) and vascular endothelial growth factor (VEGF) were more abundant in the saliva of breast cancer patients." (PMID 35798767, 2022). "OT/OTR and EGF/EGFR signalling both play critical roles during mammary gland development, and OTR signalling often overlaps with EGFR pathways, supporting the possibility of interactions of OTR and EGFR signalling in breast cancer too." (PMID 35884900, 2022). "Similarly, EGF-induced expression of the anti-apoptotic protein surviving occurs through HIF-1α, promoting resistance to apoptotic stimuli in breast cancer cells." (PMID 35158804, 2022). "Furthermore, miR-338-3p, modulated by the EGF in MCF-7 cells, promoted breast cancer cell growth and epithelial-to-mesenchymal transition, migration and invasion." (PMID 35406622, 2022). "Notably, CDDO-Me has been shown to inhibit both EGF and CCL2, consistent with our prior studies in breast cancer that reported decreased TAM numbers in tumors treated with CDDO-Me." (PMID 35265066, 2022). "Curcumin was also found to reduce EGFR activation and EGF-induced phosphorylation of ERK1/2 as well as JNK activity in breast cancer cells however, there was a lack of inhibition of p38." (PMID 34867402, 2021). "Additionally, EGF-stimulated EMT, which transforms breast cancer MDA-MB-468 cells into a mesenchymal-like shape, increases the expression of ATP-binding cassette subfamily C member 3 (ABCC3) after Ca2+ signaling of TRPC1." (PMID 33806911, 2021). "To investigate the mechanism by which EGF reduces binding of T-DM1 to cell surface HER2, which may lead to HER2-positive breast cancer cells resistance to T-DM1, we examined protein levels of HER2 in SKBR-3 cells treated with EGF, erlotinib or left untreated." (PMID 34066157, 2021). "In human breast cancer cells, MDA-MB-468, epidermal growth factor (EGF)-induced EMT is correlated with a transient elevation of cytosolic Ca2+ and accompanied by increased vimentin expression and phosphorylation of signal transducer and activator of transcription 3 (STAT3) markers of EMT." (PMID 34944940, 2021). "Moreover, we found clear evidence linking the presence of M2-like TAMs in the coculture system with the activation of EGF- and TGF-β-related intracellular signaling pathways, such as the PI3K/Akt pathway in the breast cancer cells." (PMID 34006822, 2021). "In contrast, the addition of EGF in the culture medium increased the size of tumorspheres formed by breast cancer PDX cells cocultured with Cfd-KO mADSCs but failed to rescue the number of tumorspheres formed by cocultured PDX cells." (PMID 34439392, 2021). "B6H12 treatment also acutely inhibited EGF-induced EGFR tyrosine phosphorylation in breast cancer stem cells but not in differentiated breast cancer cells." (PMID 33925464, 2021).
breast carcinoma (continued). "Similar to our previous observation in NB cells, overexpression of NLRR1 increased the cell growth in NLRR1-low-expressing MCF7 breast cancer cells and the activation of ERK in the cells was enhanced when treated with EGF and IGF in dose-dependent manner and time-dependent manner." (PMID 34277416, 2021). "Instead, we found that ERK5 silencing significantly impaired breast cancer cell invasion through the Matrigel under fetal bovine serum (FBS)-free condition or in response to EGF treatment, but not following FBS stimulation." (PMID 33981002, 2021). "Briefly, these data likely indicate that Sig-1R might be involved in the EGF-induced calcium release of MDA-NEO and MDA-HER2 breast cancer cells." (PMID 33832505, 2021). "In addition to 100 nM FIPI, different concentrations were tested and revealed that even 30 min of preincubation with 1 nM FIPI sufficiently abrogated EGF-induced calcium release in both MDA-NEO and MDA-HER2 breast cancer cells." (PMID 33832505, 2021). "Which of these PLD-dependent pathways plays a role in the EGF-induced migration of MDA-NEO and MDA-HER2 breast cancer cells remains unclear." (PMID 33832505, 2021). "Given the reported paracrine effect of soluble factors secreted by breast cancer cells on breast stromal fibroblasts —we assessed the effect of selected exogenous and paracrine growth factors (i.e., PDGF, bFGF, EGF, IGF-I and TGF-β) on the transcriptional regulation of decorin." (PMID 33924197, 2021). "Hence, calcium measurements with EGF, U73122, and FIPI were performed with both breast cancer cell lines." (PMID 33832505, 2021). "Dimethyl melaleucate and three structurally related PTs, ursolic acid, 18α-glycyrrhetinic acid, and carbenoxolone suppress EGF mediated breast cancer proliferation through sustained inhibition of EGFR and its downstream effectors STAT3 and cyclin D1 in breast cancer lines." (PMID 34681605, 2021). "In breast cancer cells, melittin was shown to suppress the EGF-induced cell motility (EGF: epidermal growth factor) and invasion by inhibiting the PI3K/Akt/mTOR (PI3K: phosphatidylinositol-3-kinase, Akt: protein kinase B, mTOR: mammalian target of rapamycin) signalling pathway." (PMID 34067049, 2021). "Our data suggest that targeting ER-β in TNBC could be an alternative approach for downregulating IGF/EGF signalling and controlling the impact of LDL in breast cancer patients." (PMID 35011656, 2021). "Hence, PLD1 activity seems necessary for EGF-induced calcium release in MDA-NEO and MDA-HER2 human breast cancer cells." (PMID 33832505, 2021). "In breast cancer, EGF (epidermal growth factor) stimulation activates CDK5 to phosphorylate Girdin (Gα-interacting vesicle associated protein) at Ser1674, which activates the downstream G-coupled receptor-dependent signaling pathway for promoting cell migration." (PMID 35006426, 2021). "In addition, proliferation of breast cancer is enhanced by insulin-like growth factor 1 (IGF-1) and epidermal growth factor (EGF), which stimulate signaling through the MAPK and PI3K/AKT pathways by activation of IGF-1R and EGFR receptors, respectively." (PMID 34462889, 2021). "However, in all cases, the degree of increase was less than that induced by EGF and was less than the changes observed in MDA-MB-468 breast cancer cells." (PMID 33322037, 2020). "Although the EMT-associated ITGB1, ITGA2 and ILK are not essential for EGF-induced EMT in PMC42-ET cells, they are necessary for breast cancer cell adhesion to ECM-substrates and cellular movement." (PMID 33276802, 2020). "Together, it seems to suggest that these candidates do not directly mediate the EMT induced by EGF in this breast cancer cell line." (PMID 33276802, 2020). "Knockdown of ANO1 in MCF-7 or T47D breast cancer cells resulted in a reduced tyrosine phosphorylation of EGFR (the site is not reported) and of STAT3 transcription factor in response to EGF, whereas overexpression of ANO1 in T47D cells increased phosphorylation EGFR and STAT3." (PMID 33250781, 2020).
breast carcinoma (continued). "Having found that many of the genes inhibited by THZ1 are regulated in an EGF-dependent manner, we hypothesized that inhibition of CDK7-mediated transcription via THZ1 could potentiate the effects of EGFR inhibition in breast cancer." (PMID 32155786, 2020). "Our study suggests that CD99-derived agonist ligands inhibit EGF-induced EGFR dimerization through impairing RhoA-Rac1 signaling-mediated reorganization of the actin cytoskeleton, thereby contributing to the suppression of breast cancer growth." (PMID 33050232, 2020). "Furthermore, EGF and TGF-β mediated osteoclastogenesis is accompanied by a sustained production of RANKL by bone stromal cells, potentially favoring breast cancer’s bone tropism." (PMID 32332763, 2020). "Furthermore, CBD restrict epidermal growth factor (EGF)-induced tumorigenic properties by inhibiting EGFR, Akt, ERK, and NF-κB signaling pathways as well as matrix metalloproteinase 2 and 9 in human breast cancer cells." (PMID 31979368, 2020). "Moreover, STAT3 can be activated by other stimulators such as EGF and VEGF, which are important in formation of stromal compartment in breast cancer." (PMID 32649314, 2020). "And that the promoting effect of TGF-β on EMT could be potentiated by oncogene HER2, epidermal growth factor (EGF), or MEK5-ERK signaling in breast cancer." (PMID 33178818, 2020). "Taken together, these results indicate that CD99-derived agonist ligand inhibits epidermal growth factor (EGF)-induced EGFR dimerization through impairment of cytoskeletal reorganization by PTPN12-dependent c-Src/FAK inactivation, thereby suppressing breast cancer growth." (PMID 33050232, 2020). "Here we demonstrated that binding of SH3BGRL to HER2 specifically enhanced the phosphorylation at Y877 in response to EGF stimulation, and Y1196 even without EGF stimulation in HER-2 high breast cancer cells." (PMID 32381043, 2020). "Therefore, our study identified a novel function for WAVE3 in the regulation of breast cancer development and progression through the modulation of a positive feedback loop between WAVE3 and PI3K-TGF-β-EGF signaling pathways." (PMID 33012785, 2020). "Besides, western blot and immunohistochemistry assays indicated that RLT-03 significantly inhibited the expression of VEGF, EGF, CD34, IL-10, and TGF-β related to the angiogenesis and inflammatory regulation of breast cancer." (PMID 32595723, 2020). "In summary, both breast cancer cell lines (MDA-MB-231 and MCF10CA1a) exhibited a directional response with EGF(−)/iEF(+) treatment by migrating faster and with greater persistence with iEFs applied in the antiparallel direction when compared with untreated controls." (PMID 31428691, 2019). "EGF activates Pyk2, regulates functions of downstream Twist‐1,2, CD44, Snail‐1,2, matrix metalloproteinase‐10 (MMP‐10), β‐catenin, fibronectin, vimentin, E‐cadherin, ZO‐1, and Zeb‐1,2, promotes EMT, migration, invasion, and metastasis of breast cancer cells." (PMID 31368612, 2019). "Inhibition of Akt activation with MK2206 nullified the pro-migratory effects of antiparallel iEFs on EGF(−) spontaneous migration of breast cancer cells, and no changes were observed in Akt activation by iEFs." (PMID 31428691, 2019). "In addition, several factors including vascular endothelial growth factor (VEGF), PC-cell-derived growth factor (PCDGF), epidermal growth factor (EGF), and CTGF were demonstrated to confer migratory and metastatic properties to breast cancer cells." (PMID 30866584, 2019). "Overall, these results showed that EGFR and EGF could inhibit the expression of AJAP1 and promot the β-catenin nuclear localization in the breast cancer cell lines." (PMID 31171012, 2019). "Similar to amphiregulin and TGF-α, EGF is reported to promote breast tumorigenesis through EGFR activation, and inhibition of EGF/EGFR signaling has been shown to exert anti-tumor effects for breast cancer." (PMID 31532771, 2019).
breast carcinoma (continued). "Our data suggests that S100 proteins, which act as Ca2+ sensors, could play a role in EGF induced tumor cell growth and metastasis, contribute to trastuzumab resistance and cell migration and that they are likely drug targets in HER2+ breast cancer." (PMID 30736768, 2019). "H3K4me1 was mapped in EGF-treated SKBR3 and BT474 breast cancer cell lines." (PMID 31747426, 2019). "α9-nAChR synergizes mainly with epidermal growth factor (EGF) receptor, insulin-like growth factor 1 (IGF-1) receptor, vascular endothelial growth factor (VEGF) receptor in lung cancer cells, and estrogen receptor α (ERα) in breast cancer cells." (PMID 31835799, 2019). "Since nuclear translocation did not occur in the majority of cell lines tested, this observation is in line with our data, indicating the lack of YB-1 translocation in breast cancer cell lines after EGF treatment." (PMID 30126195, 2018). "In response to EGF stimulation, the EGFR controls expression of hexokinase (HK1) and phosphorylation of the pyruvate kinase M2 (PKM2), two glycolytic enzymes that catalyze key steps in the pathway, thus increasing aerobic glycolysis of breast cancer cells." (PMID 29124875, 2018). "EGF is able to induce the expression of GPER in estrogen receptor negative breast cancer cells, thus facilitating a growth stimulatory effect of 17β-estradiol even in breast cancer cells lacking ERα expression." (PMID 30687231, 2018). "To determine whether atorvastatin would influence the EGF responsiveness of our breast cancer cell lines, we treated MCF-7 RFP, MDA-MB-231 RFP, and MDA-MB-231 RFP/Ecad with atorvastatin for 24 hours and then stimulated with 5nM EGF for 5 or 30 minutes." (PMID 29763460, 2018). "Another saponin species, SO-1861 from the roots of Saponaria officinalis also significantly augmented the therapeutic efficacy of EGF-Sap (Sap3-EGF, i.e., Saporin isoform 3 fused to epidermal growth factor) against the EGFR-expressing TSA mammary carcinoma cell line TSA growing in syngeneic mice." (PMID 29438358, 2018). "Finally, anti-ANXA2 mAbs significantly inhibited EGF-induced proliferation and metastasis by successfully blocking of EGFR homo-dimerization, phosphorylation and internalization in breast cancer." (PMID 29568351, 2018). "These include therapies directed against the epidermal growth factor (EGF) receptor and human epidermal growth factor receptor (HER)-2 for lung and breast cancers, B-RAF protein inhibitors in melanoma, estrogen targeted therapies in breast cancer and VEGF/VEGFR targeted therapies in prostate cancer." (PMID 30261690, 2018). "For estrogen, there is evidence that following in vitro treatment of serum-starved breast cancer cells, CSC activity is upregulated and that this is regulated by EGF, FG,F or Notch1 receptors, indicating indirect, paracrine or juxtacrine signaling between cells." (PMID 29600163, 2018). "Furthermore, they demonstrated that TMEM16A knockdown reduced the autocrine secretion of EGFR ligands, EGF and TGF-α in breast cancer cells, suggesting that TMEM16A can activate EGFR signaling by increasing autocrine secretion of EGFR-ligands." (PMID 28893247, 2017). "EGF-induced steroid hormone biosynthesis is a topic of further study as a potential mechanism of SR action in breast cancer spheroids carried in media lacking exogenously added hormones." (PMID 28412963, 2017). "Therefore, we analyzed the role of CNR2 specific agonist (JWH-015) on EGF and/or IGF-I-induced tumorigenic events in ERα- and ERα+ breast cancers." (PMID 27213582, 2017).
breast carcinoma (continued). "In breast cancer cells, endogenous levels of Rac1, PI3K and PAK1 were all stimulated following treatment with epidermal growth factor (EGF) leading to increased migration, however in cells expressing a PAK1 kinase dead mutant this migratory response to EGF was significantly diminished." (PMID 27845911, 2017). "Interestingly, in an in vitro model, EGF and FGF have been shown to drive breast cancer cell resistance to letrozole via activation of the PI3K signaling pathway." (PMID 29141657, 2017). "In addition, we show, for the first time, that CNR2 activation inhibits the activation of EGFR/IGF-IR signaling pathways and EGF/IGF-I-induced tumorigenic events in ERα- and ERα+ breast cancer subtypes in vitro and in vivo." (PMID 27213582, 2017). "Mo-IPQA at a concentration of 10 μM was effective for up to 48 h after addition and completely abolished the phosphorylation of EGFR in EGF-stimulated HCC1954 breast cancer cells, whereas its effect was limited at a concentration of 20 μM in the MDA-MB-231 breast cancer cell line." (PMID 28166195, 2017). "Our finding that the PAD inhibitor, BB-Cl-Amidine, suppresses EGF-induced tumor cell migration, raises the possibility that PAD inhibitors could function in therapeutic formulations for treating EGFR-overexpressing breast cancers." (PMID 28549415, 2017). "Similarly, 4-methyl-3-nitrobenzoic acid derivative inhibited the epidermal growth factor (EGF)-induced migration and chemotaxis of breast cancer cell lines." (PMID 27903278, 2016). "We have discovered that EGF-stimulated activation of Smad2/3 upregulated several key EMT markers, inhibited E-cadherin expression, promoted EMT, enhanced migration and invasion in MCF-7 and MDA-MB-231 breast cancer cells." (PMID 27829223, 2016). "Here, we identify an alternate mechanism utilized by metastatic breast cancer cells to activate cofilin in the absence of EGF stimulation induced PLCγ1 activation, increasing the potential pathways for inducing metastatic migration." (PMID 26620550, 2016). "Therefore, the objective of this study was to determine the mechanism of EGF-induced EMT through activating Smad2/3 in MCF-7 and MDA-MB-231 breast cancer cells." (PMID 27829223, 2016). "In this study, we exposed Luminal-A breast cancer cells in culture to combined “TME Stimulation”, representing three typical arms of the breast TME: hormonal (estrogen), inflammatory (tumor necrosis factor α) and growth-promoting (epidermal growth factor)." (PMID 27835603, 2016). "For the ER-positive human breast cancer cell line, the ganglioside content of MCF-7 cells was reported to be higher than MDA-MB-231 cells and membrane-inserted ganglioside GM3 of MCF-7 cells blocked EGF-stimulated growth." (PMID 27144558, 2016). "Unexpectedly, monitoring cytosolic and ER Zn2+ using FRET sensor proteins does not support EGF–ionomycin-triggered Zn2+ waves in breast cancer cells." (PMID 26739447, 2016). "In pulmonary metastatic model of breast cancer, Th2 CD4+ T lymphocytes that produce IL-4 and IL-13, M2-type TAMs and IMCs are activated and in turn produce EGF, thus resulting in activation of a paracrine-mediated enhancement of malignant cell invasion and dissemination." (PMID 27533463, 2016). "It has been reported that EGF stimulation of ERK is enhanced in Rat-1 cells treated with MβCD55, but in contrast MβCD treatment alone has been shown to suppress ERK activation in human breast cancer cells." (PMID 27762399, 2016). "The human breast cancer MCF-7 cells has estrogen receptor (ER) and EGF receptors, depending on estrogen and EGF for growth, and is not invasive, while human breast cancer MDA-MB-231 cells and SK-BR-3 cells are aggressive and estrogen-independent during growth." (PMID 27144558, 2016). "Therefore, it is proposed that during EGF stimulation, MICAL1, especially for its FAD domain, facilitates the production of ROS, helping to promote the migratory and invasive ability of breast cancer cells." (PMID 27430308, 2016).